AKT2 (AKT serine/threonine kinase 2)
Diseases named in the same sentence as AKT2 in open-access papers (continued):
Sharing a sentence is not in itself a finding about the gene and the disease.
inflammatory breast carcinoma (1 paper, 2019). An advanced, invasive breast adenocarcinoma characterized by the presence of distinct changes in the overlying skin. "As a result AKT1 levels are increased and AKT2 levels are decreased in inflammatory breast cancer compared to normal breast tissue." (PMID 31752925, 2019). "Astonishingly, in inflammatory breast cancer AKT3, but not AKT1 or AKT2, increases proliferation and decreases apoptosis." (PMID 31752925, 2019).
Intellectual disability (1 paper, 2023). "Four mTOR-related genes associated with intracranial volume and intellectual disability, namely, PPP2R5A, PPP2R5C, AKT2, and MTOR, are among the top list of positively selected genes in the human lineage." (PMID 37789379, 2023).
lentivirus infection (1 paper, 2017). Virus diseases caused by the Lentivirus genus. "Lipopolysaccharide-induced macrophages were challenged with NBA1-siRNA lentivirus infection and subsequent protein expression was assessed to examine the relationships among phosphorylated AKT2, NBA1, SPK1, and P-SPK1." (PMID 29383164, 2017).
lipoatrophic diabetes (1 paper, 2024). A rare syndrome characterized by almost complete absence of body fat, accentuated muscularity, insulin-resistant diabetes, hyperlipidemia, hepatomegaly, and hypermetabolism. "The relevance of this pathway in humans is emphasized by the discovery of a family with lipoatrophic diabetes carrying an AKT2 mutation." (PMID 39631563, 2024).
liposarcoma (1 paper, 2020). A usually painless malignant tumor that arises from adipose tissue. "Thus, the ectopic expression properties of the zebrafish rag2 promoter in the mesenchymal cell compartments has been used to drive expression of KRASG12D or a myristoylated constitutively active form of Akt2 in order to generate transgenic models of rhabdomyosarcoma or liposarcoma, respectively." (PMID 32759814, 2020).
lung squamous cell carcinoma (1 paper, 2020). "Although AKT2 is also highly expressed in lung squamous cell carcinoma, our study found that it was not related to the prognosis of lung squamous cell carcinoma, partially owing to the small sample size of evaluated patients." (PMID 32873299, 2020).
lymphoid tumors (1 paper, 2019). "An Akt2 inhibitor combined with GCs may be used in the future for treatment of GC-resistant lymphoid tumors." (PMID 30598523, 2019). "As inhibition of Akt2 can effectively reverse GC resistance, they may represent a novel and promising treatment to overcome GC resistance in lymphoid tumors." (PMID 30598523, 2019). "To examine the therapeutic role of Akt isoform specific inhibitors in the treatment of GC-resistant lymphoid tumor cells, we treated CCRF-CEM cells with DEX and A-674563 (Akt1 inhibitor), CCT128930 (Akt2 inhibitor), or Akti1/2 (Akt1/2 inhibitor)." (PMID 30598523, 2019). "Pharmacologic inhibition of Akt2 more effectively restores sensitivity to GCs than inhibition of Akt1 in vitro, shows higher synergistic effect acting with DEX, and reverses GC resistance in GC-resistant T- or B- lymphoid tumors in vivo with reduced liver toxicity." (PMID 30598523, 2019).
mesothelioma (1 paper, 2020). A usually malignant and aggressive neoplasm of the mesothelium which is often associated with exposure to asbestos. "Both PI3K genes, PIK3CA and PIK3CD, all 3 AKT genes, AKT1, AKT2 and AKT3, as well as BCL2 gene were detected in mesothelium and mesothelioma samples." (PMID 32664372, 2020).
metastatic melanoma (1 paper, 2015). A melanoma that has spread from its primary site to another anatomic site. "Relative to AKT1, AKT3 was upregulated and AKT2 downregulated in all the VGP and metastatic melanoma cell lines tested." (PMID 25595898, 2015).
MODY (1 paper, 2018). "In addition to known MODY genes, we report the identification of variants in RFX6, WFS1, AKT2, NKX6–1 that may contribute to development of MODY." (PMID 29439679, 2018).
myocardial infarction (1 paper, 2017). Gross necrosis of the myocardium, as a result of interruption of the blood supply to the area, as in coronary thrombosis. "Atorvastatin had a beneficial effect on cardiac remodeling following myocardial infarction by inhibiting AKT2/NBA1/SPK1-mediated macrophage recruitment, apoptosis, and collagen deposition while increasing angiogenesis in the infarct area." (PMID 29383164, 2017). "The AKT2/NAB1/SPK1 pathway is a novel regulating factor of macrophage migration and cardiac remodeling after myocardial infarction." (PMID 29383164, 2017).
myocarditis (1 paper, 2022). Myocarditis is a condition that is characterized by inflammation of the heart muscle (myocardium). "In cardiac myocytes, AKT2 is a key signaling molecule for the heart from damage through the activation of innate immunity during acute myocarditis." (PMID 35163412, 2022). "In conclusion, our study showed, for the first time, that AKT2 in cardiac myocytes participates in the pathogenesis of CVB3-induced myocarditis." (PMID 35163412, 2022). "In the present study, we examined the effect of cardiac-specific AKT2 deletion in CVB3-induced myocarditis." (PMID 35163412, 2022). "We demonstrated that AKT2 has important protective roles in the development of CVB3-induced myocarditis in response to a variety of provocative physiologic and pathologic stimuli." (PMID 35163412, 2022). "We used a cardiac-specific AKT2 knockout (KO) mouse to determine the role of AKT2 in CVB3-mediated myocarditis." (PMID 35163412, 2022). "AKT2 deletion induced severe myocarditis and cardiac dysfunction due to CVB3 infection." (PMID 35163412, 2022). "AKT2 gene silencing in cardiac myocytes induced mouse death during the acute phase of infection and increased chronic-phase cardiac inflammation and the severity of myocarditis." (PMID 35163412, 2022).
nonalcoholic fatty liver disease (1 paper, 2021). "Emodin (0.25 or 0.5 μg/ml) was reported to attenuate nonalcoholic fatty liver disease (NAFLD) in zebrafish by activating AMPK pathway, via improving PI3K/AKT2/AMPKα-mediated IR and enhancing AMPKα/PPARα/CPT1 and AMPKα/PPARα/ACOX1-mediated fatty acid oxidation." (PMID 34629100, 2021).
nutritional deficiency (1 paper, 2023). "Thus, the AKT2 would cause nutritional deficiency, inflammation, and immune dysfunction across tissues." (PMID 38097986, 2023).
pharyngeal tumour (1 paper, 2013). "Using pMDM2 (Ser 166) as an indicator of AKT2 activity matched normal and tumour oro-pharyngeal tumour sections were co-stained with pAKT (Ser 473) and this revealed a strong correlation between active AKT and pMDM2 (Ser 166) in tumour stroma compared to normal stroma." (PMID 23867201, 2013).
progeria (1 paper, 2023). "Notably, the higher levels of ATP, impaired Akt2 signaling, and low pyruvate kinase activity in human senescent and mouse progeria myoblasts were reversed by inhibition of MAT2A, suggesting that increased methionine catabolism might be affecting glycolysis." (PMID 36797255, 2023). "On the other hand, insulin phosphorylated Akt2 in WM and LMN, but failed to do so in LM cells, implicating Akt2 signaling in the insulin resistance of progeria myoblasts." (PMID 36797255, 2023).
psychosis (1 paper, 2024). "M2698, an oral dual Akt/p70S6K inhibitor with an IC50 of 1.1 nM, exhibited psychosis side effects in phase I clinical trials, potentially linked to its interaction with Akt2." (PMID 39513867, 2024). "However, it was found to cause psychosis side effects in phase I clinical trials, possibly due to its impact on Akt2." (PMID 39513867, 2024).
ptosis (1 paper, 2017). The drooping of the upper eyelid. "Both patients were also noted to have mild bilateral ptosis with proptosis, in keeping with the dysmorphic features described in two previous patients with the AKT2 p.Glu17Lys mutation." (PMID 28541532, 2017).
refractory anemia (1 paper, 2017). "Mutations in genes other than PIGA, EGFR-AS1, AKT2 and CBLC, were largely distributed in subjects with refractory anemia with excess blasts (RAEB) (n = 56) or the AML with multilineage dysplasia following MDS (MDS-AML) (n = 24)." (PMID 29137279, 2017).
reovirus infection (1 paper, 2021). "Interestingly, expression of both AKT1 and AKT2 at mRNA level was reduced after VSV or reovirus infection." (PMID 33976210, 2021). "We next knocked down AKT1, AKT2, and AKT3 and examined the expression of IFN-β in BMDC followed by VSV or reovirus infection." (PMID 33976210, 2021). "Knockdown of AKT3, but not AKT1 or AKT2, substantially reduced the enhanced expression of IFN-β at mRNA level in BMDC infected by VSV or reovirus, suggesting that AKT3 is the possible downstream target of PI3K activation after VSV or reovirus infection." (PMID 33976210, 2021).
retinal (1 paper, 2023). "Our previous study showed that the reduction in Akt1 activity in RPE contributes to the retinal vascular lesions in diabetic mice, but whether the increased Akt2 activity in DR RPE impacts disease pathology (progression) has not been investigated." (PMID 37443129, 2023).
Salmonella Infections (1 paper, 2019). Infections with bacteria of the genus SALMONELLA. "Although SopB mediates sustained activation of the pro-survival kinase Akt in infected epithelial cells, and moreover, Akt2 deficiency mice display increased susceptibility to Salmonella infection, the role of SopB in vivo is not clear to now." (PMID 31024858, 2019).
Sepsis (1 paper, 2020). Sepsis is defined as life-threatening organ dysfunction caused by a dysregulated host response to infection. "Additionally, recent studies have confirmed that glycometabolism is involved in the pathogenesis of sepsis-induced myocardial depression, and Akt2 is a crucial molecule involved in glycometabolism." (PMID 32908879, 2020). "It has been reported that after Akt2 knockdown, heart function was improved in the LPS-induced mouse sepsis model, which may be achieved by the ubiquitination of Akt2." (PMID 32908879, 2020).
sickle cell disease (1 paper, 2014). Sickle cell anemias are chronic hemolytic diseases that may induce three types of acute accidents: severe anemia, severe bacterial infections, and ischemic vasoocclusive accidents (VOA) caused by sickle-shaped red blood cells obstructing small blood vessels and capillaries. "Similarly, Akt2−/− neutrophils have been reported to exhibit decreased migration compared with WT cells, and Akt2 inhibition reduces aggregation of neutrophils and platelets isolated from patients with sickle cell disease." (PMID 25240046, 2014).
Simpson-Golabi-Behmel syndrome (1 paper, 2013). Simpson-Golabi-Behmel syndrome is a rare X-linked multiple congenital anomalies syndrome, characterized by pre- and postnatal overgrowth, distinctive craniofacial features, variable congenital malformations, organomegaly and an increased tumor risk. "The level of Akt2 protein expression is upregulated during differentiation of SGBS (Simpson-Golabi-Behmel syndrome) preadipocytes." (PMID 23951196, 2013).
soft tissue tumours (1 paper, 2017). "Although Akt1 overexpression was prominent in soft tissue tumours, it was still lower than that of Akt2 or Akt3." (PMID 28209968, 2017).
thyroid (1 paper, 2025). "Most of the 16 thyroid-related genes, in addition to several cancer-related genes including AKT2, VEGFA, ERBB2, and CCND3, were positively correlated with TDS." (PMID 41353477, 2025).
thyroid tumour (1 paper, 2017). "Akt1 or Akt2 ablation prevents thyroid tumour onset in Pten+/− mice." (PMID 28082369, 2017). "Inpp4b ablation in Pten+/− mice promotes AKT2-dependent thyroid tumour growth." (PMID 28082369, 2017).
undifferentiated carcinoma (1 paper, 2008). A usually aggressive malignant epithelial neoplasm composed of atypical cells which do not display evidence of glandular, squamous, or transitional cell differentiation.
Ureteral obstruction (1 paper, 2014). Obstruction of the flow of urine through the ureter. "In this study, we investigated the contribution of Akt2 to experimental renal EMT and fibrosis using the well-established model of unilateral ureteral obstruction (UUO)." (PMID 25148525, 2014).
viral myocarditis (1 paper, 2022). Myocarditis that is caused by an infection with a viral agent. "AKT2 regulates glucose uptake, fatty acid transport, and glycogen synthase activity, but the role of AKT2 in the development of pathologic acute cardiac damage such as CVB3-induced viral myocarditis is unknown." (PMID 35163412, 2022). "The effect of cardiac AKT2 deletion was examined in a CVB3-induced acute viral myocarditis model." (PMID 35163412, 2022). "Thus, AKT2 signaling regulated by phosphorylation of the activation loop could control CVB3-induced viral myocarditis." (PMID 35163412, 2022).
tumor (272 papers, 2002 to 2026). "Strikingly, despite differences in exon usage between species, mouse tumor samples also showed conserved depletion of A-loop-deficient isoforms (Akt2-210) and enrichment of A-loop-intact isoforms (Akt2-201) during resistance." (PMID 40681872, 2025). "For example, in transgenic mice with activated Akt1 or Akt2 expression within the mammary gland, AKT1 is predominantly associated with tumor initiation, whereas AKT2 is involved in tumor progression and metastasis." (PMID 36230716, 2022). "AKT2 has been shown to be involved in the maintenance of the tumorigenic characteristics of cells, as its knockdown was associated with tumor inhibition." (PMID 35892586, 2022). "We have previously demonstrated that activation of Akt-2 specifically, is associated with NB tumor development, progression and metastasis." (PMID 35018218, 2022). "A consensus can be drawn in that while AKT1-mediated signals are associated with cell proliferation and survival, AKT2-mediated signals are associated with metastatic progression with limited or growth inhibitory actions on the primary tumor." (PMID 33498407, 2021). "Pan-Akt inhibition sensitized tumor cells to chemotherapy, and specific blockade of Akt1 or/and Akt2 caused cells to be more chemoresponsive." (PMID 34591413, 2021). "Despite lack of total consensus, literature favors the possibility that AKT1 is involved in increased proliferation and tumor growth as well as decreased apoptosis, whereas AKT2 is associated with increased migration, invasion, and metastasis." (PMID 33498407, 2021). "Tumor aggressiveness as well as poor survival rates are particularly linked to Akt2′s amplification and overexpression." (PMID 33916378, 2021). "Recent studies demonstrated that AKT2 is an oncogene associated with tumor aggressiveness through promoting cancer cell survival and invasion." (PMID 33015042, 2020). "On the other hand, it was observed that AKT2 isoform is allied with the acquisition of stem/ progenitor properties associated with tumor invasion and migration both in 2D and 3D cellular models." (PMID 33227065, 2020). "We demonstrate by in silico analysis that Akt1 is the dominant isoform harbouring gain-of-function mutations, particularly the PH domain mutation E17K, in tumour samples, whereas Akt2 and Akt3 undergo copy number variations with higher frequency." (PMID 28209968, 2017). "It is probable that the loss of Akt1 or Akt2 was compensated for by the remaining Akt isoforms and/or alternative signaling pathways in the tumor cells." (PMID 23919516, 2013). "Dual stained cells were counted in stroma associated with normal and tumour tissue and demonstrated a significant increase in the proportion of AKT2 positive cells, that were also positive for pAKT (Ser 473) in tumour associated stroma." (PMID 23867201, 2013). "In our study we found that loss of either Akt1 or Akt2 produced a small but significant delay in tumor onset and a small but significant decrease in tumor growth rate." (PMID 23919516, 2013). "It is of note that from the analysis of TMAs we found that aberrant expression of more than a single gene within the PI3K pathway (PTEN loss, overexpression of AKT1, AKT2 or p110α, respectively) was observed only in tumours showing AKT activation." (PMID 23408974, 2013). "In two independent diabetic mouse models (streptozotocin injection for type I disease and Akt2-deficient mice for type II disease), high levels of blood glucose generated larger tumour volumes presumably due to increased tumour demand." (PMID 21699706, 2011). "Moreover, PAD1 gene silencing, inhibition of AKT2 citrullination, and AKT2 mutation all decrease the tumor-initiating ability of OC cells both in vitro and in vivo." (PMID 40847455, 2025). "Overall, their data showed that miR-194 acts as a tumor suppressor in colorectal carcinogenesis by targeting the PDK1/AKT2/XIAP pathway and could be an important diagnostic and prognostic biomarker for CRC43." (PMID 36854781, 2023).